SLC7A5 (solute carrier family 7 member 5)
Diseases named in the same sentence as SLC7A5 in open-access papers (continued):
Sharing a sentence is not in itself a finding about the gene and the disease.
tumor (continued). "To enhance our insights into the prognostic validity of the five-gene signature, we examined the expression of ATP6AP1, SLC7A5, EPDR1, SDC1, and PIGR in 13 paired BC samples, comparing them with their adjacent non-tumor tissues through RT-PCR." (PMID 38162504, 2023). "Existing SLC transporter inhibitors mostly focused on tumor cells, and targeting SLC1A5, SLC3A2, or SLC7A5 has shown anti-tumor efficacy." (PMID 37277776, 2023). "The three remaining genes represented two solute carrier transporters (SLC27A1 and SLC7A5) for amino acids and fatty acids and one membrane bound protease (ANPEP) that plays a role in tumour invasion and metastasis." (PMID 37495601, 2023). "Among several amino acid transporters in cells, SLC7A5 (L-type amino acid transporter 1, LAT1), a neutral amino acid transporter that is highly expressed in tumor cells, is mainly responsible for BPA uptake." (PMID 36371738, 2023). "Our study suggests that SLC7A5 promotes the proliferation and metastasis of TNBC cells by promoting the tumor-related EMT." (PMID 37731509, 2023). "Another study demonstrated that the tumor-promoting lncRNA MINCR promotes proliferation and migration and suppresses apoptosis in NSCLC cells by negatively regulating the miR-126/SLC7A5 axis." (PMID 35757505, 2022). "Conversely, exosomes from sh-LINC01614 transduced CAFs inhibited tumor growth in the xenografts, accompanied by a reduced expression of Ki67, SLC38A2, and SLC7A5." (PMID 36209111, 2022). "Our finding highlights that miR-194 exerts a tumor-suppressive role in digestive system cancers by targeting ATP6V1F, PPP1R14B, BTF3L4 and SLC7A5." (PMID 36620589, 2022). "As ZNF24 has been proven to promote the growth of SLC7A5-mediated KRAS mutant LUAD cells in vitro, we established a nude mouse transplanted tumor model for in vivo experimental verification." (PMID 36505791, 2022). "By plotting the tumor growth curve and comparing tumor volumes, we observed that knocking down ZNF24 significantly inhibited the growth of A549 cell-transplanted tumors, while SLC7A5 overexpression after ZNF24 knockdown partially reversed tumor inhibition." (PMID 36505791, 2022). "Consistently, LINC01614 was abundant in CAFs, and LINC01614 expression of tumor cells was positively correlated with the density of α-SMA+ CAFs and the expression of SLC38A2 and SLC7A5 in tumors." (PMID 36209111, 2022). "Transcriptome sequencing and Genome-wide CRISPR/Cas9 proliferation screening confirmed that miR-194 play tumor suppressive roles in GIC mainly by targeting ATP6V1F, BTF3L4, PPP1R14B and SLC7A5." (PMID 36620589, 2022). "The difference in the expression of the five ADME genes (SLC16A1, SLC7A5, SLCO1B1, CYP17A1, and ABCC8) between tumor and normal tissues was significant and was closely correlated with the survival of patients with NSCLC." (PMID 34522968, 2021). "MYC and SLC7A5 constitute a feedback loop to amplify MYC transcriptional program, and sustain essential amino acid (EAA) metabolism in tumour cells." (PMID 34195095, 2021). "Studies have reported that SLC7A5, SLC1A5, SLC3A2, SLC43A1 and SLC43A2 are the major BCAA transporters in tumor cells." (PMID 33882453, 2021). "Through the upregulation of SLC7A5, YAP1/TAZ are able to increase mTORC1 activity and tumor proliferation and survival." (PMID 33953707, 2021). "Hypoxia is a key feature of the tumor microenvironment and tumor infiltrated NK cells are enriched for hypoxia signatures, including expression of HK2, SLC7A5, SLC2A3, and KDM3A." (PMID 34177887, 2021).
tumor (continued). "In tumor cells, the expression of c-MYC has been shown to significantly decrease after the JPH203-mediated inhibition of SLC7A5, thereby affecting the metabolic function controlled by c-MYC." (PMID 34977008, 2021). "Upregulated expression of SLC7A11 (10/14), SLC1A5 (7/14), SLC7A5 (6/14), and SLC3A2 (5/14) was observed in most of the tumor tissues; however, GLS in LUSC, KIRC, and KICH and GLS2 in KIRC and LIHC, were significantly downregulated." (PMID 34573287, 2021). "In addition, Slc7a5 is essential for T cell differentiation and clonal expansion, correlated to negative outcomes and growth of many proliferating tumor cell types, and causes embryonic lethality in Slc7a5 knockout mice." (PMID 33164746, 2020). "Downregulation of LAT1 (SLC7A5) suppresses methionine input, thus reducing the level of cellular SAM, resulting in methylation depletion of some histones and inhibition of tumor growth." (PMID 33511116, 2020). "Three other amino acid transporters are highly expressed in tumor cells, including LAT1/SLC7A5, ATB0,+/SLC6A14, and xCT/SLC7A11." (PMID 33019627, 2020). "We previously identified the expression of the amino acid carrier SLC7A5 to be preferentially induced by the HIF2α isoform in RCC cells, providing a molecular basis for the pro-proliferative activity of HIF2α in these tumor cells." (PMID 33321829, 2020). "Tumor cells achieve high intracellular concentrations of glutamine primarily through upregulation of glutamine transporters including SLC1A5 and SLC7A5." (PMID 31652923, 2019). "While SLC7A5 mRNA expression was not predictive of BCSS in any specific molecular class, high expression of SLC7A5 protein was only predictive of shorter BCSS in ER+ high proliferation (p = 0.007) and HER2+ tumours (p = 0.03)." (PMID 29566741, 2018). "In tumor cell proliferation, HIF-2α was reported to be a critical transcriptional factor which enhances SLC7A5 expression via binding to its proximal promoter." (PMID 29422900, 2018). "In addition, the expression levels of HK2, LDHA, Glut1, and PDK1 were significantly decreased in the tumor tissues of MKN45R and HGC27R cells in the sh-SLC7A5 group." (PMID 40133832, 2025). "SLC7A5 is also overregulated in LC that might also function as an HBV receptor, regulating the tumor immune microenvironment." (PMID 41440381, 2025). "Furthermore, it has been confirmed that efficient uptake of glutamine and leucine through SLC1A5, SLC7A5, and SLC3A2 can enhance metabolic capacity and effector functions of NK and T cells targeting tumors for improved tumor recognition and infiltration." (PMID 39951434, 2025). "However, genetic deletion of SLC7A5 in activated T cells severely compromises GVT response, while dietary restriction of L-Leu controls tumor growth and further maintains GVT response." (PMID 40399490, 2025). "Moreover, Ki67 staining showed that the proliferation ability of tumor cells in vivo was also significantly inhibited after knockout of SLC3A2 and SLC7A5." (PMID 38267663, 2024). "Of all mentioned SLCs, only SLC7A5/6/7 and SLC43A2 revealed a negative association with overall survival, suggesting their high expression contributes to tumor progression." (PMID 38182561, 2024). "Therefore, amino acid transporters, including SLC1A5, SLC7A5, SLC7A11, and SLC6A14, MCTs and GLUTs have been found to be highly expressed in tumor tissues." (PMID 39850557, 2024). "Besides SLC7A5, the transporter SLC43A2 is also involved in methionine uptake in tumor cells allow them to outcompete T cells for limited methionine availability." (PMID 37277776, 2023). "Despite its low boron content (5%), L-BPA is taken up preferentially in tumor cells by L-type amino acid transporter 1 (LAT1, SLC7A5), efficiently delivering boron to target tumors with T/N~2:1, following administration of up to 700 mg/kg dose in clinical trials." (PMID 37444386, 2023).
tumor (continued). "Concerning glutamine homeostasis, up-regulation of the specific transporter ASCT2 (SLC1A5) or the more generic L-type amino acid transporter 1 (LAT1, also known as SLC7A5), was observed in HCC tissue compared with adjacent non-tumor tissue, correlating with tumor size." (PMID 37108625, 2023). "The combination of a SLC7A5 blockade mediated via JPH203 treatment and an anti-programmed cell death 1 (PD-1) antibody synergistically increased the immune cell infiltration rate and inhibited tumor progression." (PMID 37731509, 2023). "Furthermore, we correlated LINC01614 expression with tumor glutamine transporters, as detected by immunostaining for SLC38A2 and SLC7A5 and CAF infiltration as denoted by α-SMA immunostaining in 10 cases of patients with LUAD." (PMID 36209111, 2022). "Since RAS signaling is closely related to malignant tumor proliferation, we hypothesized that ZNF24 may promote the progression of KRAS mutant LUAD by upregulating SLC7A5 protein expression." (PMID 36505791, 2022). "Moreover, SLC7A5 and SLC3A2 enhance the metabolic capacity and effector function of tumor-directed CAR-NK and T cells." (PMID 36090994, 2022). "The main function of solute carrier family 7 member 5 (SLC7A5) is to help specific amino acids pass through cell membranes, provide nutrition for tumor cells, and participate in related metabolic pathways." (PMID 36505791, 2022). "Fuchs and Bode hypothesized that LAT1 provides essential amino acids for tumor growth and proliferation and is overexpressed in cancer tissues via the mTOR signaling pathway, whereas SLC1A5 drives the function of SLC7A5 through glutamine delivery." (PMID 33783998, 2021). "Indeed, LLGL2 was required for the surface localization of SLC7A5, suggesting that LLGL2 promotes tumor growth by upregulating nutrient transporters to enhance nutrient uptake within a nutrient-limited microenvironment." (PMID 33953707, 2021). "SLC7A5 and SLC3A2 were expressed at relatively high levels in 22Rv1 castration-resistant orthografts following chronic ADT (modelling clinical castration-resistant disease), while SLC1A5 was preferentially expression in CWR22Res tumours following acute ADT." (PMID 33237350, 2020). "SLC7A5 and SLC1A5 mRNA expression was consistent with that observed at protein level, i.e. elevated SLC7A5 and reduced SLC1A5 levels in the castration-resistant 22Rv1 tumours." (PMID 33237350, 2020). "In multivariate Cox regression analysis, SLC7A5 mRNA was a predictor of shorter BCSS independent of tumour size, grade or lymph node stage (p = 0.006) but not in any specific subtype." (PMID 29566741, 2018). "In contrast, positive correlation between SLC7A5 and the glutamine synthase enzyme GLUL was observed in luminal A tumours, suggesting that this subtype might rely on glutamine neosynthesis rather than uptake." (PMID 29566741, 2018). "When comparing the levels of SLC7A5 mRNA expression in the intrinsic (prediction analysis of microarray 50 (PAM50)) subtypes, high expression was observed in basal-like, HER2+ and lLuminal B tumours (p < 0.001)." (PMID 29566741, 2018). "We observed that 65.3% (47/72) of the tumor specimens showed obviously high expression of SLC7A5, while, in the non-cancerous tissues, only 13.8% (10/72) cases showed high SLC7A5 level." (PMID 27846244, 2016). "Similarly, most of the tumor tissues expressed in high level for both CRKL and SLC7A5, which is consistent with the result discovered in GC cell lines." (PMID 27846244, 2016). "Reportedly, glucose and amino acids are increased in tumor cells to meet the increased demand for robust proliferation, for example, by the induction of SLC2A1 and SLC5A1 for glucose, and by the induction of SLC7A5 for amino acids." (PMID 24718268, 2014). "We demonstrate that SLC7A5 deletion affected T cell activation, expansion and survival, and reduced IFNγ and granzyme B expression, thus controlling aGVHD, but without effect on tumor growth." (PMID 40399490, 2025).
tumor (continued). "Furthermore, TP63+ SLC7A5+ HNSCC subpopulation may resist phagocytosis by macrophages through the CD24-SIGLEC10 axis, promoting tumor escape." (PMID 39234254, 2024). "Furthermore, in the MB49 orthotopic tumor model, we found that either inhibition of AhR, IDO1 or SLC7A5 could achieve synergistic effect with cisplatin." (PMID 37670034, 2023). "Without modifying transcript level of SLC7A5 for serine import, LF tumours increased transcript levels of proton-coupling folate transporter (PCFT) to enhance exogenous folate uptake under lactate-acidified microenvironment and to compensate folate-deficit condition." (PMID 36615660, 2022). "Expressions of four transcripts including L-type amino acid transporter 1 (SLC7A5), the high-affinity L-glutamine transporter (SLC1A5), glutaminase (GLS), and glutamate dehydrogenase 1 (GLUD1) were all significantly up regulated in T3 as compared with T1 and T2 tumours." (PMID 36615660, 2022). "In this respect, the L-type amino acid transporter 1 (LAT1, SLC7A5), which is expressed at a relatively high level at the blood-brain barrier (BBB), blood-retinal barrier (BRB), testis, bone marrow, placenta and several types of human tumour is an intriguing way for targeting a drug to these organs." (PMID 32377929, 2020). "Similarly, high expression of SLC7A5 mRNA was significantly associated with hormone receptor negative (ER- and PgR-) and HER2+ tumours (all p < 0.001)." (PMID 29566741, 2018). "However, SLC7A5 protein was significant only in the ER+ high-proliferation tumours (p = 0.02) and not in any other subtypes (data not shown)." (PMID 29566741, 2018). "Therefore, SLC7A5 could be one of the downstream genes of CRKL in SGC-7901 cells, which leads the tumor cells to proliferate, invade and migrate." (PMID 27846244, 2016). "Differences arise in the immediate outputs—glutaminolysis via SLC7A5 in NSCLC, fatty-acid activation via ACSL3 in CRC, and pro-migratory signaling via RAC3—and in whether CAFs act primarily by secreting a writer versus inducing tumor writers through growth-factor signaling." (PMID 41280938, 2025). "However, Mayers and colleagues found decreased SLC7A5, BCAT1, BCAT2 and BCKDH expression in PDAC tissue, and loss of BCAT2 does not affect PDAC tumor formation." (PMID 33882453, 2021). "In particular, the amino acid transporters SLC1A5 and SLC7A5 as well as the ancillary subunit SLC3A2, which are required for efficient uptake of glutamine and leucine respectively, could strengthen the metabolic capabilities and effector functions of tumor-directed CAR-NK and T cells." (PMID 33953707, 2021). "SLC7A5 protein expression was associated with negative hormone receptor status and HER2+ tumours (all p ≤ 0.002) and it was highly expressed in triple negative (TN) and basal-like phenotype malignancies compared to non-TN and non-basal-like tumours (p < 0.001)." (PMID 29566741, 2018). "Using patient-derived tumor and adjacent non-cancerous tissues, we found that expression of the SLC1A5, SLC7A5, and SLC38A1, and NUPR1 is a rescue mechanism induced by GLS inhibition." (PMID 40707944, 2025). "Using patient-derived tumor and adjacent non-cancerous tissues, we confirmed that expression of the SLC1A5, SLC7A5, and SLC38A1 is a rescue mechanism induced by GLS inhibition." (PMID 40707944, 2025). "To determine if upregulation of this transporter was important to patient outcome in LUAD, we assessed the levels of SLC7A5 in three LUAD datasets; BCCRC (n = 77 pairs), TCGA RNA-seq (n = 562; 503 tumor, 59 non-malignant), and KMplotter (n = 720 tumor)." (PMID 37318751, 2023). "The levels of the main methionine transporters of CD4 T cells, including SLC7A5 and CD988, which form a heterodimeric structure comprising SLC7A5 and SLC3A2, were not markedly reduced in tumor-infiltrated CD4 T cells compared to those in CD4 T cells from tumor-free mice." (PMID 37147330, 2023).
infection (8 papers, 2013 to 2026). The state of being infected such as from the introduction of a foreign agent such as serum, vaccine, antigenic substance or organism. "However, as infection progressed, IL-13 levels recovered in T cell-specific SLC7A5-deficient mice, alongside resistance." (PMID 41809569, 2026). "Indeed, we observed that after putrescine, spermidine, or spermine supplementation, the levels of Cat1, Cat2, Slc3a2, and Slc7a5 suffered some alterations, suggesting that infection and polyamines can influence transporter genes’ transcription." (PMID 37000792, 2023). "Meanwhile, we observed that certain biomarkers (SLC7A5, PDE4D, CXCR4, PER1, PIK3R1, HBA1, HBB) were elevated during the pre-infection phase (LTBI), while others (SOCS3, GZMK, HIS1H3B) were upregulated in the post-infection phase (ATB)." (PMID 40589756, 2025). "Furthermore, B-cell lymphoma 2 (BCL-2) and solute carrier family 7 member 5 (SLC7A5) genes, involved in apoptosis and autophagy, respectively, have been discovered to be up-regulated after infection with the wild type of a virulent strain." (PMID 38920683, 2024). "On day 15 of infection, Ag-expCD4+ T cells expressed lower levels of Glut-1 (a glucose transporter), CD98 (a component of the Slc7a5 heterodimeric large neutral amino acid transporter), and CD71 (a transferrin receptor) than Ag-expCD4+ T cells from day 5 of infection." (PMID 32817333, 2020). "Moreover,we found increased SLC7A5 and IDO1 expression in rhesus andhuman blood, suggesting that peripheral leukocytes catabolize tryptophaninto kynurenine during infection." (PMID 41180073, 2025).
adenocarcinoma (3 papers, 2011 to 2019). A common cancer characterized by the presence of malignant glandular cells. "Of the canonical changes noted, promoter (PR) DM loci with reciprocal changes in expression in adenocarcinomas included HBEGF, AGER, PTPRM, DPT, CST1, MELK; DM GB loci with concordant changes in expression included FOXM1, FERMT1, SLC7A5, and FAP genes." (PMID 26683690, 2015). "The most basal-enriched ion transporter gene, SLC7A5/LAT1, is a cationic amino acid transporter that has previously been used to distinguish squamous lung cancer from adenocarcinoma." (PMID 21572528, 2011).
genetic disorders (1 paper, 2014). "No Slc7a5 mutations associated with inherited human diseases have been reported (perhaps unsurprising given that the gene appears to be essential for mammalian embryonic development), although some other members of the SLC7 family are linked with genetic disorders." (PMID 24586861, 2014).
SLC7A5 also shares sentences with these, for which no sentence is quoted: autism (3 papers); adenoma (2); Alzheimer disease (2); bile duct adenocarcinoma (2); esophageal cancer (2); invasive breast carcinoma (2); leukemia (2); lymph node metastasis (2); meningioma (2); neurodevelopmental disorder (2); osteosarcoma (2); phenylketonuria (2); viral infection (2); actinic keratosis (1); acute GVHD (1); adrenocortical cancer (1); alcoholic liver diseases (1); alcoholism (1); allergic asthma (1); Allergy (1); asthma (1); brain cancer (1); brain tumors (1); bronchioalveolar carcinoma (1); cardiomyopathy (1); cataract (1); cervical squamous cell carcinoma (1); chronic myeloid leukaemia (1); colorectal (1); Crohn disease (1).
A further 41 diseases each share a sentence with SLC7A5 in 1 paper.